MTIF2 (mitochondrial translational initiation factor 2)
Description:
Mitochondrial translation initiation factor that promotes binding of formylmethionyl-tRNA to the 30S ribosomal subunits (By similarity). Also involved in the hydrolysis of GTP during the formation of the 70S ribosomal complex (By similarity).
Synonyms: IF-2Mt
Tractability: Small molecule: a structure with a bound ligand is known. PROTAC: ubiquitination databases record sites on it; its protein half-life has been measured.
Gene: Protein-coding gene on chromosome 2 (55,236,230 to 55,270,263, reverse strand). Ensembl gene ENSG00000085760.
Subcellular location: Mitochondrion
Subcellular location (Human Protein Atlas): Mitochondria
Pathways (Reactome):
Metabolism of proteins: Mitochondrial translation initiation
Gene Ontology:
Molecular function: RNA binding; translation initiation factor activity; ribosomal small subunit binding; translation factor activity, RNA binding; GTP binding; GTPase activity
Biological process: formation of translation preinitiation complex; mitochondrial translational initiation; ribosome disassembly; translational initiation
Cellular component: mitochondrion; mitochondrial matrix
Genetic constraint (gnomAD): Loss-of-function variants: 62 observed, 75.19 expected, observed/expected ratio (o/e) 0.82, 90% interval 0.67 to 1.02. The upper end of that interval is the gene's LOEUF score, 1.02, which puts it in group 4 of 6, group 1 being the genes least tolerant of losing a copy. Missense variants: 921 observed, 847.7 expected, observed/expected ratio (o/e) 1.09, 90% interval 1.03 to 1.15. Synonymous variants: 307 observed, 289.85 expected, observed/expected ratio (o/e) 1.06, 90% interval 0.96 to 1.16.
Homologues: Orthologues: chimpanzee MTIF2 (99% identical), macaque MTIF2 (92% identical), pig MTIF2 (86% identical), dog MTIF2 (85% identical), guinea pig MTIF2 (84% identical), rat Mtif2 (83% identical), mouse Mtif2 (81% identical), rabbit MTIF2 (76% identical), tropical clawed frog mtif2 (63% identical), zebrafish mtif2 (57% identical), Drosophila melanogaster mIF2 (45% identical). Paralogues in human: EEF1A1 (15% identical), EEF1A2 (15% identical), EEF2 (14% identical), EFL1 (14% identical), EFTUD2 (13% identical), TUFM (13% identical), GFM2 (13% identical), GSPT1 (13% identical), HBS1L (13% identical), EIF5B (13% identical), GTPBP1 (13% identical), GSPT2 (13% identical), and 6 more.
Diseases named in the same sentence as MTIF2 in open-access papers:
MTIF2 is named in the same sentence as 8 diseases in open-access papers, as found by Europe PMC text mining. Sharing a sentence is not in itself a finding about the gene and the disease. The quoted sentences say what the papers report.
lung carcinoma (1 paper, 2022). "Another study targeted gene associated with lung cancer and found four key genes that may affect lung cancer prognosis: MTIF2, ACOX1, CAV1, and MRPL17." (PMID 35039759, 2022).
osteosarcoma (1 paper, 2020). A usually aggressive malignant bone-forming mesenchymal neoplasm, predominantly affecting adolescents and young adults. "In this study, we have identified MRPS7 and MTIF2 as hub genes involved in the metastasis of osteosarcoma." (PMID 32665038, 2020). "Therefore, protein synthesis involved in MRPS7 and MTIF2 within the mitochondrion might also have a potential connection with the development of osteosarcoma." (PMID 32665038, 2020). "Some of these genes have been reported as biomarkers for osteosarcoma, while the role of HLA-DRA, MTIF2, MRPS7 and CDK20, should also be further systematically investigated based on actual diseased tissues or even cell lines and animal models." (PMID 32665038, 2020).
tumor (3 papers, 2022 to 2024). "Genes and proteins regulating the TCA cycle (PDHA1, SUCLG2, SUCLG1, and IDH2) as well as mitochondrial function (VDAC1, MRPS31, LARS2, OPA1, and MTIF2) showed higher transcripts and protein levels in Wnt‐high compared with Wnt‐low tumor entities." (PMID 35904277, 2022). "Downregulation of MTIF2 affects tumor cell proliferation and migration." (PMID 36466838, 2022). "In addition, the drug resistance of tumor cells is weakened, the overexpression of MTIF2 and ICD-related DAMPs is significantly reduced, DC maturation/activation is impaired, tumor immunosuppression occurs, and tumor cells rapidly proliferate and patients have a poor prognosis." (PMID 36466838, 2022). "Mitochondrial Translational Initiation Factor 2 (MTIF2) is highly expressed in HCC and serves as a central tumor immune infiltration gene, inhibiting DC maturation by reducing the release of DAMPs after 5-fluorouracil (5-FU) treatment." (PMID 39334927, 2024).
cancer (1 paper, 2021). A tumor composed of atypical neoplastic, often pleomorphic cells that invade other tissues. "Notably, the roles of DES and MTIF2 at genetic or epigenetic levels are unclear in human cancers." (PMID 34323415, 2021).
mitochondrial disease (1 paper, 2021). "Previous studies have found a relationship between MTIF2 and cardiomyocyte death, but no mutation of the MTIF2 gene leading to mitochondrial diseases has been found." (PMID 34277617, 2021).
MTIF2 also shares sentences with these, for which no sentence is quoted: alcohol dependence (1 paper); conduct disorder (1); deafness (1).